PCDHB18P (protocadherin beta 18 pseudogene)
Description:
Potential calcium-dependent cell-adhesion protein.
Synonyms: PCDH-psi2; formerly PCDHB18
Gene: Transcribed unprocessed pseudogene on chromosome 5 (141,234,551 to 141,236,918, forward strand). Ensembl gene ENSG00000146001.
Subcellular location: Cell membrane